CD4 (CD4 molecule)
Diseases named in the same sentence as CD4 in open-access papers (continued):
Sharing a sentence is not in itself a finding about the gene and the disease.
tumor (continued). "Immunosuppression of the TME is also partly imposed by (but not limited to) pro-tumor CD4+ Treg and Th2 polarization." (PMID 41310721, 2025). "CD4+ Th2 cells are essential regulators of immunity and inflammation, and their role in shaping the tumor microenvironment has been well documented." (PMID 40004479, 2025). "The focus is on understanding CD4+ T-cell subtypes, their functional roles in tumor progression and suppression, and the application of novel drug delivery systems to selectively regulate these cells." (PMID 40860882, 2025). "CD4+ T cells are the dominant target tumor cells in the immune system, and dysfunction of CD4+ T cells can enable adaptive immune resistance, resulting in tumor immune escape and metastasis." (PMID 40746894, 2025). "After intradermal administration, the micelles promoted secretion of pro‐inflammatory cytokines (i.e., IFN‐γ, TNF‐α, IL‐4, IL‐6, IL‐12) and increased tumor infiltration of CD4+ and CD8+ T cells for robust antitumor immune responses." (PMID 41287898, 2025). "Flow cytometry indicated that vaccination of the tumor-bearing CD4-depleted mice appeared to generate a potent E7-specific CD8 T cell response, although a significant difference was not seen compared to the unvaccinated group." (PMID 40533862, 2025). "The overall increase in Tregs within the tumor microenvironment is driven by TGFβ-induced polarization of naïve CD4+ T cells." (PMID 40698077, 2025). "Taken together, these data suggest the tumor immune microenvironment – particularly the ratio of CD4/CD8 cells – is preserved during ex vivo culture of resection LTFs." (PMID 40791544, 2025). "Studies have shown that oral administration of Akkermansia muciniphila can increase the recruitment of CCR9+CXCR3+CD4+ T lymphocytes to the tumor bed, thereby restoring the efficacy of PD-1 inhibitors in NSCLC patients." (PMID 40406244, 2025). "The tumor tissue from CGRPKO mice also had a significant increase in tumor-infiltrating CD4+ T cells, cytotoxic CD8+ T cells, and NK1.1+ NK cells as compared to wild-type mice." (PMID 40376000, 2025). "In the total tumor area, there were also more T-cells positive for membrane CD4 in high serum IGF-1 cases compared with low IGF-1 cases." (PMID 41184420, 2025). "Since it has been demonstrated that tumor-infiltrating CD4+ T effector cells can be activated by TME signals, the presence of the two cell types is not an exception." (PMID 40092980, 2025). "Immunohistochemical analysis of tumor tissues revealed significantly higher scores for NK cells, CD4+ T cells, and CD8+ T cells in the combination treatment group compared to the other groups." (PMID 39979981, 2025). "In lung squamous cell carcinoma, a new subpopulation of CD3-/CD4+ cells, characterized by the high expression of FoxP3 and TNFα, has been identified, suggesting their proinflammatory role in the tumor immune microenvironment." (PMID 40292277, 2025). "The genomic mutation and methylation of most OAS genes have been shown to alter their expression levels, which is associated with the levels of infiltrated CD4+ T cells and CD8+ T cells in the tumor microenvironment." (PMID 40366856, 2025). "CD8+ T cells (cytotoxic T lymphocytes) can directly kill targeted tumor cells, while CD4+ T cells (helper T cells) play an important role in adaptive immune regulation and are key in tumor immunotherapy." (PMID 41381536, 2025). "CD4+ T cells of the Th1 subset are essential for effective anti-tumor immunity by their secretion of cytokines such as IFN-γ, which enhance DC function and T cell cytotoxicity, and support the licensing of DCs through CD40–CD40L interactions." (PMID 41374974, 2025). "T helper (CD4+) and Treg (FoxP3+) cells were very low (1–2 cells/mm2 and undetectable, respectively) in control non-tumor samples, while they were significantly more abundant in cancer samples." (PMID 40703808, 2025).
tumor (continued). "During the effector phase of anti-tumor immunity, CD4 + lymphocytes can directly kill tumor cells while releasing cytokines to activate tumor-killing immune cells, indirectly eliminating tumor cells." (PMID 40587482, 2025). "The ability of VZV-vax to enhance CD8+ T cell responses against a co-delivered tumor-specific antigen was surprising as the anti-gE response after VZV-vax is strongly biased toward CD4+ Th1 cells and antibodies." (PMID 40280970, 2025). "We found that the proportion of CD4+CD25+FoxP3+ Tregs in the tumor tissues was remarkably decreased in the ICD 4T-1 cells group compared to that in the PBS group." (PMID 40283929, 2025). "CD8+ cytotoxic T cells are key players in directly killing tumor cells, while CD4+ helper T cells orchestrate immune responses by activating other immune cells." (PMID 40453074, 2025). "With CRT-NP, decrease in tumor infiltration of Treg cells (CD4+ FOXP3+) cell was observed as well as increase in IFNγ expression on CD4+ T cells." (PMID 40386779, 2025). "For the group of patients with esophageal cancer, CD8 + T, CD4 + T, and NK cell infiltration levels in the tumor were evaluated both before and after neo-adjuvant therapy with chemo-radiotherapy." (PMID 40277786, 2025). "CD8+ T cells recognize and kill tumor cells, exerting an anti-tumor effect, whereas CD4+ T cells assist in and regulate immune responses but can also inhibit immune reactions, facilitating tumor immune evasion." (PMID 40458394, 2025). "Many studies have shown that CD4+ helper T cells participate in anti-tumor immune responses and play a key role in determining tumor responsiveness to immune checkpoint blockade immunotherapy." (PMID 39931056, 2025). "Across multiple cancer types, CAF subsets with antigen-presenting capacity have been shown to activate CD4+ T cells and modulate tumor immunity." (PMID 41514658, 2025). "In contrast, the complete reversal of the combination therapy's anti-tumor effect was observed only when CD4+ T cells were depleted." (PMID 40426190, 2025). "Given the increased expression of GzmB, IFNγ and TNFα by M002-treated CD4+ T cells, and their tumor reactivity, we next determined if these CD4+ T cells were capable of mediating killing of tumor cells beyond their conventional helper activity." (PMID 39885128, 2025). "The increase in inflammatory status, combined with the release of tumor-associated antigens induced by the treatment, implies the activation of CD137+ T cells, particularly CD4+CD137+ T cells, which secrete the pro-inflammatory cytokine interleukin 4 (IL-4)." (PMID 41428121, 2025). "Recent advances in scRNA-seq technology, in combination with bulk RNA-seq data, now permit the characterization of tumor-infiltrating CD4+ T cells at the single-cell level." (PMID 41008548, 2025). "These events synergized with ICD to elevate the overall radioimmunotherapeutic efficacy, substantially promoting DC maturation and enhancing the infiltration of CD8+ and CD4+ T cells into tumor tissues." (PMID 40525676, 2025). "Tregs are immune-suppressive T cells characterized by high expression of FOXP3, CD25, and CD4, which play an important role in suppressing anti-tumor immunity." (PMID 40696413, 2025). "Then, we examined the proportions of CD8+ T cells and CD4+ T cells among the tumor-infiltrating T cells." (PMID 40944197, 2025). "LAG-3 is another immune checkpoint that inhibits T cell function and is expressed on tumor-infiltrating lymphocytes (CD4+ and CD8+ T cells), Treg cells, NK/T cells, B cells, NK cells, plasmacytoid DC (pDCs), and TAMs." (PMID 39915447, 2025). "Around tumor cells in stomach cancer models, you can find CD4+FoxP3− T cells, CTLA-4 T cells, and PD-L1 T cells." (PMID 40422244, 2025). "By shaping the fate of tumor-specific CD4+ Tfh cells, tumor neoantigen-induced tumor-specific B cells increase the effector functions of CD8+ T cells." (PMID 40959278, 2025).
tumor (continued). "Imiquimod, a TLR7/8 agonist, stimulates natural killer cells to eliminate tumor cells, which release tumor antigens and stimulate CD4+ T cells specific to the tumor." (PMID 40727443, 2025). "By contrast, simultaneous knockdown in both tumor cells and CAFs more substantially reduced CAFs and markedly enhanced CD4+/CD8+ infiltration, accompanied by tumor shrinkage." (PMID 41514658, 2025). "Flow cytometry analysis further revealed that combined therapy significantly increased the frequency of MECA-79+ TA-HECs and MECA-79+CD62P+ TA-HECs and tumor infiltration of Tbet+ICOS+ Th1-like CD4+ T cells and CD8+ T cells." (PMID 40460830, 2025). "Immunofluorescence staining revealed a significant increase in both CD8+ T cells and CD4+ T cells in the tumor tissues of mice treated with CuB (0.5 or 1 mg/kg)." (PMID 40896699, 2025). "Conversely, cytotoxic CD4+ T cells can also kill tumor cells in an MHC class II-independent fashion through a mechanism involving dendritic cells (DCs) and innate cells in the TME." (PMID 40543509, 2025). "Confocal IF revealed that control-treated tumors showed whole-tumor presence of CD4+ T cells while cytotoxic CD8+ T cells were restricted to the periphery." (PMID 41041061, 2025). "We also examined the presence of tumor-specific CD4+ and CD8+ T lymphocytes that produce IFN-γ and IL-10 in the spleens and lymph nodes of OpdA-treated animals." (PMID 41019059, 2025). "Another study characterized H3 G34-mutant DHG as a tumor with a higher level of immune cell infiltration, with higher levels of monocytes and CD4+ T cells, but lower Treg infiltration." (PMID 40075726, 2025). "Tumour vaccines represent a therapeutic strategy aimed at eliminating tumour cells by activating or enhancing the immune response against the tumour, including the expansion of antigen-specific CD4+ and CD8+ T cells." (PMID 40994140, 2025). "Elevated levels of CD20+ B cells facilitate antibody production that mediates ADCC through NK cells, and present antigens to CD4+ T cells, thereby contributing to tumor cell clearance." (PMID 40264767, 2025). "In contrast, the proportions of CD4+ T and CD8α+ T cells within the tumor were extremely low (< 1%)." (PMID 41208884, 2025). "Although there were fewer immunocytes in the regressing tumor, there was also a decrease in the CD4:CD8 ratio and an increase in the intratumoral GzmB:CD3 ratio, suggesting that STR was driven by cytotoxic CD8+ T-cells." (PMID 40594889, 2025). "Meanwhile, CD8+ T cells have cytotoxic effects on antigen presenting cells, they can also inhibit the anti-tumor effect of CD4+ cells by producing inhibitory cytokines." (PMID 40787472, 2025). "Overexpression of MerTK in TNBC syngeneic mouse models leads to a marked delay in tumor growth, coupled with significant increases in anti-tumor M1 macrophage, CD4+ T cell, active CD8+ T cell, active NK cell, and NKT cell populations." (PMID 40391157, 2025). "Genes such as FUOM and H2BC21 were positively correlated with immunosuppressive M2 macrophages and activated CD4 memory T cells, while negatively correlated with anti‐tumor immune cells such as resting CD4 memory T cells and activated dendritic cells." (PMID 40817807, 2025). "Meanwhile, the density of YAP1-positive cells in the tumor parenchyma was positively correlated with the density of CD4-positive cells and FOXP3-positive cells (r = 0.635, P = 0.02; r = 0.573, P = 0.04)." (PMID 40051494, 2025). "Conversely, the numbers of CD4 + T cells and natural killer cells (NKs) were reduced in both the pre-tumor and HCC groups." (PMID 40057751, 2025). "Of particular interest was the discovery of an immunologically active tumor–normal interface enriched in plasma B cells and Th2-like CD4+ T cells, characterized by specific immunometabolic signatures." (PMID 40557160, 2025). "Induction of MHCII has been shown to elicit prolonged anti-tumour immune response as it promotes activation of CD4 + cells." (PMID 40956795, 2025).
tumor (continued). "Th1 cells, a subset of CD4+ T cells, can enhance anti-tumor immunity by producing IFN-γ, which can promote apoptosis and inhibit angiogenesis." (PMID 40281780, 2025). "TLS in tumor microenvironment (TME) usually includes a B cell zone surrounded by a T cell zone composed of a mixture of CD4+ and CD8+ T cells and dendritic cells (DCs) as well as natural killer (NK) cells." (PMID 40335494, 2025). "Th1 cells differentiate from natural CD4+ Th0 cells dependent on cytokine, and their cytokine production can suppress the tumor-promoting microenvironment." (PMID 40741411, 2025). "Complementary immunofluorescence staining of tumor tissues revealed significant downregulation of the Ki-67 proliferation marker across treatment groups, accompanied by enhanced CD4+ and CD8+ T cell infiltration." (PMID 41322146, 2025). "This suggests that the overrepresentation of Treg/Tfh CD4 T cells in the tumor, was in part due to the increased proportion of CXCL13+Tfh cells." (PMID 39932553, 2025). "This was attributed to higher tumor infiltration of CD4+ and CD8+ T cells, DCs, NK and NKT cells, and the reduction of Tregs, suggesting a comprehensive combinatorial effect on the immune response." (PMID 40370435, 2025). "CD4 T cells are known to contribute to anti-tumor responses by providing help to induction of cytotoxic CD8 T cells and stimulating their effector and memory functions." (PMID 40151616, 2025). "Studies have shown that cDC2s are vital for priming anti-tumor CD4+ T cells in various tumor models." (PMID 40432108, 2025). "This in vivo licensing mechanism facilitates both MHC class I-restricted presentation to CD8+ T cells and class II-restricted presentation to CD4+ T cells, driving a coordinated and polyclonal anti-tumor immune response." (PMID 41374974, 2025). "Elevated C5a promotes tumor progression, partly through a marked reduction in CD4+ and CD8+ T cell infiltration, while lower levels appear to exert opposing effects." (PMID 40951345, 2025). "Transcriptome sequencing of tumor tissues from 25 patients revealed distinct immune micro-environments: H-CEA patients showed elevated resting memory CD4+ T cells, while L-CEA patients showed increased T follicular helper cells." (PMID 40960294, 2025). "Here, we detected, in blood, T cell responses against a broad range of MHC class I and class II tumor epitopes, suggesting the ability of UCPVax to enhance both CD4+ and CD8+ T cell diversification in vaccinated patients." (PMID 40543509, 2025). "In bladder cancer, CD4+ T cells facilitate tumor invasion through the ERβ/c-MET and ERβ/IL-1/c-MET pathways." (PMID 40303343, 2025). "It has been shown that the degree of CD4+T cell infiltration in a tumor is directly related to a favorable patient outcome regardless of immunotherapy." (PMID 40176817, 2025). "After transferring cell type annotations to the CD4 T cell subset, we identified 6 distinct CD4+ T cell populations in the combined tumor-blood dataset." (PMID 39932553, 2025). "The stabilization of HIF-1α in CD4+ T cells improves the effect of anti-PD-1 therapy to reduce tumor growth and patient survival." (PMID 41413686, 2025). "Among the various immune cell subsets involved in antitumor responses, CD4+ T cells play a pivotal role in modulating the tumor microenvironment." (PMID 40558520, 2025). "In contrast, FUOM negatively correlated with resting CD4 memory T cells (r = −0.38, p < 0.01) and activated dendritic cells (r = −0.35, p < 0.01), indicating its potential role in impairing anti‐tumor immunity." (PMID 40817807, 2025). "To confirm this, we looked at tumor infiltrating T cell profile using flow cytometry and observed CD4+ FOXP3+ Treg cells increased significantly (~9.5 folds) in D14 biopsy samples compared to pretreatment sample, i.e. D0." (PMID 40386779, 2025). "In lymphocytes, CD4+ Th1 cells are also an essential subset that activates the anti‐tumor effect of CTLs." (PMID 40257446, 2025).
tumor (continued). "The most pronounced trend observed following M3258 treatment was a reduction in M2 macrophages (p = 0.0996); less prominent reductions were observed for tumor abundance of CD4+ T cells (p = 0.247) and CD8+ T cells (p = 0.247)." (PMID 40507366, 2025). "The tumor growth rate was significantly slower in the Asparaginase + anti-PD-L1 group and the Asparaginase + anti-PD-L1 + anti-CD4 group compared to the Control group." (PMID 41229436, 2025). "LZTS3 expression is related to the reduction of the cytotoxic CD8+ T cells, the early effector playing anti-cancer effects 16,17, and increase of Treg cells, an CD4+ T subpopulation that contributes to tumor immune escape 18,19." (PMID 39744581, 2025). "We found that the numbers of activated MDSCs (CD11b+Gr‐1+) and Tregs (CD4+CD25+Foxp3+) among the tumor‐infiltrating lymphocytes in the MAP treatment group were significantly reduced." (PMID 39499771, 2025). "This can be explained by a requirement for CD4+ T helper cells to convert them to IFNγ-producing cells resulting in effective tumor therapy and reduction of Tregs." (PMID 40813233, 2025). "Specifically, NLRP3 signaling in TAMs drives the differentiation of CD4+ T cells into tumor-promoting Th2, Th17, and Treg cells, while inhibiting the polarization of Th1 cells." (PMID 40756366, 2025). "Flow cytometric analysis indicated a significant increase in the number of tumor-infiltrating CD4+ and CD8+ T cells in the MEKi+RT group." (PMID 41368644, 2025). "Previous studies have linked the proliferation of peripheral effector T cells to favorable outcomes in immunotherapy, and an increase in tumor-specific CD8+ and CD4+ effector T cells within peripheral tissues is advantageous for inhibiting tumor progression." (PMID 39888994, 2025). "Pathological complete response (pCR) patients exhibited expanded TIL populations, especially CD8+ and CD4+ T cells, indicating their cytotoxic role in tumor elimination." (PMID 40867511, 2025). "Follicular helper CD4 T cells (CD4fh) and regulatory T cells (Tregs) were identified, which play an important role in the suppression of the tumor immune response." (PMID 40725420, 2025). "Ectonucleoside triphosphate diphosphohydrolase-1 (ENTPD1), also known as CD39, is an ectonucleotidase that generates adenosine, thereby suppressing the anti-tumor activities of CD4 and CD8 T-cells, as well as NK cells." (PMID 40236693, 2025). "Consistent with subcutaneous model, Map3k7-silenced tumors were reduced in weight, infiltrated with more total and activated effector (CD44highKi-67+) CD4+ and CD8+ T cells, and less tumor associated macrophages (TAMs), which were more M1-polarized." (PMID 41280086, 2025). "This cascade of events leads to adaptive responses, including increased tumor infiltration by tumor antigen-specific CD4+ and CD8+ effector T cells and memory T cells." (PMID 40386779, 2025). "Research indicates that PLGA nanoparticles containing tumor antigens or immune adjuvants can foster antigen-specific CD4+ T-cell proliferation and cytokine release, thereby intensifying the Th1-mediated anti-tumor response." (PMID 40860882, 2025). "SD tumors exhibited substantial CD4+ T cell presence, particularly at the tumor periphery, with CD8+ T cells similarly restricted to peripheral regions indicating an immune excluded phenotype." (PMID 41041061, 2025). "As CD4+ T cell immune infiltration increases, the tumor typically progresses to later stages, with tumor size also increasing." (PMID 40004489, 2025). "Using B16F10 subcutaneous tumor models, their report demonstrated that administration of an anti-CD4 antibody had strong anti-tumor effects, which were completely reversed by CD8+ T cell depletion." (PMID 40243581, 2025). "While the increased CD4+ T cells were predominantly suppressive, they eventually exhibited an overall positive tumor suppressive effect." (PMID 40611261, 2025).